SLC7A11 (solute carrier family 7 member 11)
Diseases named in the same sentence as SLC7A11 in open-access papers (continued):
Sharing a sentence is not in itself a finding about the gene and the disease.
tumor (continued). "Metabolic alterations induced by T cells can influence the fate of GBM cells through SLC7A11, while tumor metabolism further contributes to immune evasion by impairing T cell activation via SLC7A11-mediated dysfunction." (PMID 39040097, 2024). "Conversely, ERO1α overexpression-induced xenograft tumor development and ferroptosis inhibition were significantly attenuated with suppression of SLC7A11." (PMID 38610018, 2024). "The use of ferroptosis inducers to inhibit solute carrier family 7 member 11 (SLC7A11) or glutathione peroxidase 4 (GPX4) activity can enhance the sensitivity of tumor cells to radiotherapy (RT)." (PMID 39392831, 2024). "Biologically, MLN4924 combination with SLC7A11 inhibitor Imidazole Ketone Erastin (IKE) enhanced suppression of tumor growth." (PMID 38959043, 2024). "It has been reported that Nrf2 can target and regulate Gpx4, and among the tumor suppressors that regulate ferroptosis, Nrf2 regulates the level of SLC7A11 to control the expression of GPX4." (PMID 38149613, 2024). "PDAC cells with both DNMT3B overexpression and SLC7A11 silencing had significantly less tumor-sphere formation compared to cells with only DNMT3B overexpression." (PMID 38811540, 2024). "SLC7A11 (Solute Carrier Family 7 Member 11, also known as xCT) is a key component of cystine transporter and plays an increasingly essential role in regulating tumor ferroptosis." (PMID 38605214, 2024). "Consistently, methylated FUBP1, PDK1, and SLC7A11 were also more robustly expressed in tumor tissues." (PMID 39146021, 2024). "The pharmacological inhibition of systemic Xc− in tumor cells demonstrated a compensatory increase in SLC7A11 expression, similar compensatory elevation was also induced by erastin while GSH content was declined." (PMID 38561847, 2024). "Increased SLC7A11 levels (increased cysteine transport), coupled with reduced cystine levels in tumor tissues highly suggested an enhanced cystine metabolism." (PMID 38959043, 2024). "SLC7A11 appears to represent a potential Achilles heel for tumor targeting; however, several challenges still need to be addressed." (PMID 39040097, 2024). "Initially, we analyzed publicly available databases TCGA and GTEx to assess the relevance of LAPTM4B and SLC7A11 in tumor samples compared to adjacent normal tissue." (PMID 38902268, 2024). "IHC staining revealed elevated expression of the dithiosulfatide-related protein SLC7A11 in tumor tissue." (PMID 38191330, 2024). "This led to the release of IFN-γ, which effectively inhibited the expression of SLC3A2 and SLC7A11 in tumor cells." (PMID 38853203, 2024). "The mediation effect of SLC7A11 on ERO1α-regulated cell growth and angiogenesis was further verified in vivo using a subcutaneous xenograft tumor model." (PMID 38610018, 2024). "As one of the DRGs, SLC7A11 upregulating plays an essential role in promoting disulfidptosis and tumor development, which is harmful for cancer patients." (PMID 38185671, 2024). "A study revealed that IFNγ derived from immunotherapy-activated CD8+ T cells act synergistically with radiotherapy to inhibit SLC7A11 which results in reduced cystine uptake, and increased tumor lipid oxidation and ferroptosis, thereby tumor suppression." (PMID 38705513, 2024).
tumor (continued). "CircEPSTI1 is upregulated in cervical cancer cells, and its knockdown decreases tumor growth in vivo and in vitro and activates ferroptosis via the circEPSTI1/miR-375_miR409-3P_miR-515-5p/SLC7A11 pathway." (PMID 38778030, 2024). "The combination of MLN4924 and SLC7A11 inhibitor IKE effectively blocks tumor growth, revealing a sound therapeutic strategy." (PMID 38959043, 2024). "In Slc7a11-KD tumors, the tumor-infiltrating CD8+ T cells was markedly increased, accompanied by a reduction in CD8+ T-cell ferroptosis." (PMID 38360744, 2024). "As an upregulated circRNA in lung adenocarcinoma, circP4HB ectopic expression increases tumor growth and suppresses ferroptosis via the circP4HB/miR-1184/SLC7A11." (PMID 38778030, 2024). "The significant abundance of SLC7A11 suggests its potential as a promising target for tumor therapy." (PMID 39040097, 2024). "Recent studies have revealed that high expression of SLC7A11 promotes tumor growth, partly by suppressing ferroptosis." (PMID 38534739, 2024). "In line with this, it has been shown that radiotherapy can activate ATM, leading to the inhibition of SLC7A11, reduced cysteine uptake, ferroptosis activation, and tumor growth retardation." (PMID 38778030, 2024). "TRIM7 induced K48-linked polyubiquitination of SLC7A11 protein, further leading to the inhibition of its downstream GPX4 and acting as a tumor suppressor in GC." (PMID 38509147, 2024). "Among these, the SLC7A11 was identified, with substantial literature evidence, to be involved in ferroptosis and tumor progression." (PMID 38172959, 2024). "Many cysteine transporters, such as Cysteinyl-tRNA synthetase (CARS) and SLC7A11, involve in tumor ferroptosis." (PMID 38575922, 2024). "It is noteworthy that SLC7A11 is prominently expressed in numerous tumors and exerts influence on tumor progression, invasion, metastasis, and unfavorable prognosis." (PMID 39040097, 2024). "SLC7A11 expression level was high within tumor tissues and was connected to the infiltration of eosinophil, CD8+ T-cell, and macrophages, which was associated with poor overall survival." (PMID 39350768, 2024). "SLC7A11 has been revealed to defend against oxidative stress and promote cancer proliferation, and its inhibition induces tumor cell death under elevated intracellular ROS." (PMID 38353724, 2024). "SLC7A11 expression can also be repressed by transcription factors that take part in tumor suppression." (PMID 39125992, 2024). "In more detail, EGCG exerts these functions via suppressing the stimulatory effects of STAT1 on SLC7A11 promoter, leading to ferroptosis in A549 cells and restricting tumor growth in vivo." (PMID 39104501, 2024). "Inhibition of the cystine/GSH/GPX4 pathway induces ferroptosis and suppresses tumor growth with SLC7A11 as a hub of this axis." (PMID 38959043, 2024). "Deletion of SLC7A11 induces tumor-selective ferroptosis and inhibits the growth of pancreatic ductal adenocarcinoma (PDAC) growth." (PMID 39600338, 2024). "Afterwards, we isolated total RNA from tumor tissues in order to examine the levels of circUPF2 and SLC7A11 using qRT‒PCR." (PMID 38811968, 2024). "A novel form of programmed cell death, known as disulfidptosis, was identified last year; tumour cells with high SLC7A11 expression undergo disulfidptosis when deprived of glucose." (PMID 39590840, 2024).
tumor (continued). "Given the pivotal role of SLC7A11 in cancer treatment, this paper provides an overview of its structure and biological functions, as well as its involvement in oxidative stress, tumor metabolism, immune modulation, and cell death." (PMID 39040097, 2024). "The other frequently mutated tumor suppressor, BAP1, which encodes a deubiquitinating enzyme, reduces histone H2A ubiquitination on the SLC7A11 promoter region to repress SLC7A11 expression and consequently promotes ferroptosis." (PMID 38908072, 2024). "A recent study demonstrated that the level of SLC7A11 expression determines the sensitivity of cancer cells to oxidative stress, uncovering the context-dependent role of SLC7A11 in tumor biology." (PMID 39605832, 2024). "Tumor cells with high SLC7A11 expression uptake a large amount of cystine to meet their metabolic needs." (PMID 39415848, 2024). "SLC7A11 presents itself as a viable target for tumor therapy, with two primary strategies currently under consideration." (PMID 39040097, 2024). "In summary, we have demonstrated that aberrantly activated mTORC1 contributes to ferroptosis resistance and tumor growth by regulating of the ERO1α/IL-6/STAT3/SLC7A11 signaling pathway." (PMID 38610018, 2024). "For instance, the secretion of interferon gamma (IFN-γ) by CD8+ T cells has been shown to down-regulate the expression of SLC3A2 and SLC7A11 in tumor cells, leading to a disruption in cystine uptake." (PMID 39040097, 2024). "The in silico analysis also revealed an upregulation of SLC7A11 in BTC patients, which was associated with higher pathological tumor grading, disease progression and worse outcome, in contrast to the in silico findings for CD71." (PMID 38603713, 2024). "Upreregulation of SLC7A11 suppresses ferroptosis through cystine and promotes the growth of tumor cells." (PMID 38226966, 2024). "The inhibition of the SLC7A11-GSH pathway has been shown to have a significant anti-tumor effect in various types of human cancers." (PMID 39807126, 2024). "Together, these data demonstrate that the PRMT5-FUBP1- PDK1/SLC7A11 axis is enhanced in tumor cells." (PMID 39146021, 2024). "Second, the determination of how to define a baseline SLC7A11 expression level is a critical core of tumor treatment strategies based on SLC7A11 expression levels." (PMID 39040097, 2024). "To begin, we analyzed the relative expression of SLC7A11 in over 10,000 tumor and normal tissue samples in the TCGA and GTEx databases." (PMID 38655266, 2024). "HMOX1, p-NRF2, and SLC7A11 were expressed at higher levels in the GW9662-treated tumor tissues than in the control tumor tissues." (PMID 38786003, 2024). "This approach capitalizes on the heightened vulnerability of SLC7A11-overexpressing tumors to glucose and glutamine deprivation, ultimately leading to tumor cell death." (PMID 39040097, 2024). "Compared with normal tissues, the relative expression of GPX4, SLC7A11, and Fer1 was significantly upregulated in tumor tissues (p < 0.001)." (PMID 39155888, 2024). "Increased expression of SLC7A11 has been associated with inferior 5-year survival of patients with NSCLC, and SLC7A11 silencing decreases the tumor volume in nude animal models." (PMID 38778030, 2024). "Immunotherapy-activated CD8+ T cells can release IFN-γ to downregulate the system Xc− functional subunits SLC3A2 and SLC7A11, impeding tumor cells from acquiring cystine and thus leading to lipid peroxidation and ferroptosis in cancer cells." (PMID 39614322, 2024). "Interferon γ (IFNγ), released by CD8 T cells, downregulates the expression of SLC3A2 and SLC7A11, promoting lipid peroxidation and ferroptosis in tumor cells." (PMID 39600338, 2024).
tumor (continued). "In this study, we also observed that the expression level of SLC7A11 in tumor tissue of patients with HCC was significantly higher than adjacent benign tissue, as evident with the TCGA database and tissue samples from patients with HCC." (PMID 38399303, 2024). "To explore the impact of impeding tumor competition for cystine on T cell anti-tumor immunity, we generated Slc7a11 knockdown (KD) B16F10 cells." (PMID 38360744, 2024). "SLC7A11 is generally upregulated in tumor cells, particularly in those chemotherapy/radiotherapy-resistant tumor cells." (PMID 38740771, 2024). "Studies have demonstrated that the combination of FINs targeting GPX4 and SLC7A11 inhibition with radiotherapy can increase tumor cell ferroptosis, thereby augmenting the tumor-killing effects of radiation." (PMID 39769177, 2024). "In tumor cells, Keap1 inactivation promotes ferroptosis resistance following activation of the SLC7A11/cysteine/GSH axis by stabilizing Nrf2 and its target genes." (PMID 39125992, 2024). "Significant differences in the human papillomavirus status, perivascular infiltrate distribution, radiotherapy, and primary tumor site location were observed between the high- and low-expression groups of SLC7A11." (PMID 39350768, 2024). "The release of IFNγ by CD8+ T cells has been found to down-regulate the expression of SLC7A11, thereby restricting cystine uptake by tumor cells and promoting tumor cell lipid peroxidation and ferroptosis." (PMID 38655266, 2024). "Consistent with the in vitro results, SLC7A11 re-expression abrogated the suppressive effects of ERO1α depletion on xenograft growth, tumor cell proliferation (as assessed by the Ki-67 index), and tumor angiogenesis (as assessed by the CD31 index)." (PMID 38610018, 2024). "Proinflammatory cytokine IL-1β can induce overexpression of solute carrier family 7 member 11 (SLC7A11) in HCC cells to enhance tumor metastasis." (PMID 38397901, 2024). "Given SLC7A11 is a potential oncoprotein, we selected 13 receptor proteins with known putative tumor suppressor function, and silenced them individually by a pool of three independent siRNAs." (PMID 38959043, 2024). "As a species of high-metabolism and high-energy-consumption cell, tumor cells with high SLC7A11 expression exhibit a stronger disulfidptosis response when glucose is depleted." (PMID 39091494, 2024). "We found that SLC7A11 was expressed at higher levels in KIRP tumor tissues as well as in the high-FRI group." (PMID 38534739, 2024). "The ERO1α/IL-6/STAT3/SLC7A11 pathway is crucial for mTORC1-mediated ferroptosis resistance and tumor growth, and combining ERO1α inhibition with ferroptosis inducers is a novel and effective treatment for mTORC1-related tumors." (PMID 38610018, 2024). "CD8+ T cells are the main producers of interferon-γ, which suppresses the expression of SLC7A11, thereby promoting the ferroptosis and the peroxidation of lipids in tumor cells." (PMID 39350768, 2024). "Further examination of the tumor samples by immunohistochemistry revealed increased SLC7A11 staining in LAPTM4B-positive tumor samples." (PMID 38902268, 2024). "As a key regulator of disulfidptosis, SLC7A11 has been evidenced to enable to protect tumor cells from oxidative stress, and presents overexpression in many cancers." (PMID 39605832, 2024). "Cancer cells can augment tumor growth by upregulating SLC7A11 expression and inhibiting ferroptosis through diverse mechanisms (Koppula, Zhuang & Gan, 2021)." (PMID 38317842, 2024). "Numerous studies have shown that SLC7A11 has become a central hub between ferroptosis and tumor suppression." (PMID 38189879, 2024). "Here we demonstrate that tumor cells outcompete T cells for cystine uptake due to high Slc7a11 expression." (PMID 38360744, 2024).
tumor (continued). "SLC7A11 primarily influences tumor cell viability by modulating the cellular response to oxidative stress." (PMID 39600313, 2024). "Sulfasalazine (SSZ), a potent and particular inhibitor of SLC7A11, can suppress tumor growth by inhibiting the Xc- system and reducing intracellular levels of GSH." (PMID 38994627, 2024). "In silico gene expression analysis of CD71 and SLC7A11 showed significantly higher expression in tumor tissue compared to normal control tissue and correlation analysis also showed a significant linear positive correlation between CD71 and SLC7A11." (PMID 38603713, 2024). "This pathway then increases the transcription of the SLC7A11 gene and results in ferroptosis resistance, tumor cell proliferation, and angiogenesis." (PMID 38705513, 2024). "The expression of SLC7A11 in tumor cells can be inhibited by IFN‐γ released by CD8+T cells, resulting in enhanced ferroptosis and improved efficacy of immunotherapy." (PMID 39660409, 2024). "Erastin-mediated inhibition of SLC7A11 induced ferroptosis in cells with ELF3 overexpression and PTEN deficiency and thus inhibited cell colony formation and tumor development." (PMID 39695109, 2024). "Elevated levels of SLC7A11 expression have been demonstrated in a diverse array of tumor types, such as lung, liver, pancreatic, breast, ovarian, prostate, bladder, colorectal, melanoma, and leukemia, in comparison to healthy tissues." (PMID 39040097, 2024). "At present, scientists have observed that SLC7A11 induces different cell death patterns in different tumor cells." (PMID 38443363, 2024). "To evaluate the level of ferroptosis, we measured the amounts of MDA, our data indicated that patients’ tumor samples with low expression of either LAPTM4B or SLC7A11 had higher MDA levels." (PMID 38902268, 2024). "The tumor sample analysis showed that SLC7A11 and GPX4 mRNA expression were notably decreased in G−LPQDEA/shSLC7A11-treated tumors compared to the control group." (PMID 38399303, 2024). "Combination of KCTD10 activation or USP18 inactivation with SLC7A11 inhibition appears to be an effective approach to inhibit tumor growth." (PMID 38959043, 2024). "Although many studies indicated that SLC7A11 overexpression leads to tumor progression, some studies revealed that SLC7A11 downregulation results in resistance to chemotherapy." (PMID 38705513, 2024). "In a study on KRAS-mutant LUAD cells, it was found that SLC7A11 is overexpressed in these cells and mediates tumor progression." (PMID 38705513, 2024). "Because SLC7A11 is frequently overexpressed in human malignancies and plays a significant role in ferroptosis resistance and tumor progression, it is critical to explore how SLC7A11 expression is controlled." (PMID 38610018, 2024). "Targeted inhibition of SLC7A11 promotes intracellular lipid peroxide accumulation, induce tumor cell ferroptosis, and enhances sensitivity to immunotherapy, radiotherapy, and chemotherapy." (PMID 38738174, 2024). "Immunohistochemical results showed that compared with the normal tissues, SLC7A11 was highly expressed in tumour tissues." (PMID 39170701, 2024). "Recent studies indicate that overexpression of SLC7A11 partially promotes tumor growth by inhibiting ferroptosis." (PMID 39193375, 2024). "As a sodium-independent cystine-glutamate antiporter, system Xc- and its key component SLC7A11, previous studies suggest that overexpression of SLC7A11 inhibits ferroptosis to promote tumor growth." (PMID 38956409, 2024).